CCDC17 (coiled-coil domain containing 17)
Synonyms: FLJ33084
Tractability: No criterion of Open Targets' tractability assessment is met for any kind of drug.
Gene: Protein-coding gene on chromosome 1 (45,620,044 to 45,624,058, reverse strand). Ensembl gene ENSG00000159588.
Subcellular location: Cell projection, cilium; Cytoplasm, cytoskeleton, cilium axoneme
Gene Ontology:
Molecular function: protein binding
Cellular component: axoneme; cilium
Genetic constraint (gnomAD): Loss-of-function variants: 79 observed, 62.7 expected, observed/expected ratio (o/e) 1.26, 90% interval 1.05 to 1.52. The upper end of that interval is the gene's LOEUF score, 1.52, which puts it in group 6 of 6, group 1 being the genes least tolerant of losing a copy. Missense variants: 846 observed, 774.95 expected, observed/expected ratio (o/e) 1.09, 90% interval 1.03 to 1.15. Synonymous variants: 376 observed, 321.46 expected, observed/expected ratio (o/e) 1.17, 90% interval 1.07 to 1.27.
Homologues: Orthologues: chimpanzee CCDC17 (99% identical), macaque GPBP1L1 (82% identical), rat Ccdc17 (60% identical), mouse Ccdc17 (59% identical), guinea pig CCDC17 (58% identical).
Diseases named in the same sentence as CCDC17 in open-access papers:
CCDC17 is named in the same sentence as 1 disease in open-access papers, as found by Europe PMC text mining. Sharing a sentence is not in itself a finding about the gene and the disease. The quoted sentences say what the papers report.
Chronic pain (1 paper, 2025). Persistent pain, usually defined as pain that has lasted longer than 3 to 6 months. "Among the 42 new chronic pain loci that harbor protein-coding variants, five genes (HECTD3 (chr1.p34.3), CCDC17 (chr1.p34.3), DNM1 (chr9.q33.1), PCDHA1 (chr5.q31.5), and WDR90 (chr16.p13.3)) showed evidence of colocalization in more than one brain tissue." (PMID 40297705, 2025).